ITGA2 (integrin subunit alpha 2)
Diseases named in the same sentence as ITGA2 in open-access papers (continued):
Sharing a sentence is not in itself a finding about the gene and the disease.
ovarian carcinoma (23 papers, 2015 to 2024). A malignant neoplasm originating from the surface ovarian epithelium. "ITGA2 overexpression facilitates the growth of ovarian cancer, confers paclitaxel resistance, and is associated with poor prognosis in PDAC tumors." (PMID 39682235, 2024). "L. Ma and others found that high expression of ITGA2 can promote ovarian cancer cell proliferation and resistance to paclitaxel through the AKT/FOXO1 signaling axis." (PMID 38751445, 2024). "Recently, a study highlighted that high expression of ITGA2 promotes ovarian cancer cell proliferation and resistance to albumin paclitaxel through the AKT/FOXO1 signaling axis." (PMID 37386391, 2023). "Among the identified proteins, significant enhanced expression of GFPT2, FLNA, TGFBI (CDGG1), ITGA2 predicted unfavorable prognosis in ovarian cancer patients." (PMID 36463238, 2022). "With reference to carcinogenesis, in particular ovarian cancer, a role for ITGA2 in spheroid formation is described, thus promoting metastasis in the peritoneal cavity." (PMID 34827207, 2021). "In summary, our in-depth glycoproteomic analysis offers a detailed and site-specific glycosylation signature of human ITGA2 in ovarian cancer cells." (PMID 34646995, 2021). "We have previously suggested a new route of peritoneal dissemination through the interaction of integrin alpha 2 (encoded by ITGA2) with collagen I and III usually enriched in the omental tumor of ovarian cancer patients." (PMID 34646995, 2021). "We provide evidence that ITGA2 is a highly glycosylated transmembrane protein expressed in ovarian cancer tissue and cell lines." (PMID 34646995, 2021). "Here, we suggest a new route of metastasis through the interaction of integrin alpha 2 (ITGA2) with collagens enriched in the tumor coinciding with poor outcome in patients with ovarian cancer." (PMID 33026975, 2020). "Encouragingly, our results showed that the sensitivity of ovarian cancer cells to albumin paclitaxel improved significantly after we knocked down ITGA2 expression." (PMID 32202508, 2020). "Colony formation and MTS assays revealed that the overexpression of ITGA2 significantly improved the proliferation ability of ovarian cancer." (PMID 32202508, 2020). "The ITGA2 gene is highly expressed in ovarian cancer, as established by transcriptomics and histochemistry studies of the ovary and single follicles." (PMID 32202508, 2020). "To determine the clinical relevance of ITGA2 in ovarian cancer, we assessed 70 paraffin-embedded, archived ovarian cancer tissues immunohistochemically (IHC)." (PMID 32202508, 2020). "In this study, we confirmed that ITGA2 was elevated in ovarian cancer, which led to poor prognosis and survival." (PMID 32202508, 2020). "Consistent with our findings from the Western Blot analysis, we established that ITGA2 was markedly overexpressed in ovarian cancer." (PMID 32202508, 2020). "In ovarian cancer cells, expressions of ITGA2 enhance AKT phosphorylation and further accelerate the phosphorylation of the oncogenic protein FOXO1." (PMID 32899691, 2020). "To explore the biological role of ITGA2 in the progression of ovarian cancer, we knocked down ITGA2 in SKOV3, OVCAR3, and A2780 cell lines." (PMID 32202508, 2020). "We used the SKOV3 cell line to study the biological role of ITGA2 in PTX resistance in ovarian cancer in vivo." (PMID 32202508, 2020). "Then, we conducted cell biology function and animal experiments to reaffirm the promoting role of ITGA2 in the proliferation of ovarian cancer cells." (PMID 32202508, 2020). "Although previous studies have shown that ITGA2 increases in ovarian cancer, the specific molecular mechanism of how ITGA2 promotes ovarian cancer proliferation and metastasis is still unclear." (PMID 32202508, 2020). "Collectively, our study suggests that aberrant expression of ITGA2 increases ovarian cancer cell proliferation and enhances ovarian cancer cell resistance to albumin paclitaxel through the AKT/FOXO1 signaling axis." (PMID 32202508, 2020).
ovarian carcinoma (continued). "Lastly, we sought to identify the mechanism by which ITGA2 enhances the spread of ovarian cancer cells." (PMID 32202508, 2020). "Colony formation and MTS assays indicated that knocking down ITGA2 significantly inhibited the proliferation ability of ovarian cancer." (PMID 32202508, 2020). "Given the potential therapeutic targets of ITGA2, we systematically explored the significance of ITGA2 overexpression in ovarian cancer." (PMID 32202508, 2020). "Our research results provide a reasonable explanation for ITGA2’s stimulation of the proliferation of ovarian cancer cells." (PMID 32202508, 2020). "In regards to ovarian cancer, a recent study demonstrated that ovarian cancer cells with elevated ITGA2 led to poor prognosis and survival." (PMID 33026975, 2020). "Overall, these observations suggested that the expression of the adhesion-related genes ITGA2 and VEGFC may be associated with the increased adhesiveness of M-Met5A cells toward ovarian cancer cells." (PMID 36766725, 2023). "Notably, a recent study demonstrated that ITGA2 promotes peritoneal metastasis of ovarian cancer through collagen-mediated cell adhesion and focal adhesion signaling." (PMID 36766725, 2023). "Therefore, we evaluated the impact of ITGA2 sialylation in the context of ovarian cancer by examining sialylated protein expression in human-derived primary ovarian and metastatic tumors." (PMID 34646995, 2021). "Importantly, available ChIP-Seq data of MECOM in human ovarian carcinoma cells also showed direct binding to the promotor regions of Col4a2 and Itga2." (PMID 33762742, 2021). "Firstly, we verified that the expression level of ITGA2 in ovarian cancer is indeed elevated." (PMID 32202508, 2020). "The mechanism of how ITGA2 is up-regulated in ovarian cancer, therefore, requires further research." (PMID 32202508, 2020). "Moreover, a knockdown assay of ITGA2 has shown that sensitivity of paclitaxel is improved in paclitaxel-resistant ovarian cancer cells." (PMID 32899691, 2020). "Additionally, our study of the human protein atlas web tool revealed that ITGA2 correlated significantly with the unfavorable prognosis of ovarian cancer patients." (PMID 32202508, 2020). "In addition, transcriptomic analysis of the TCGA-ovarian cancer dataset revealed a positive correlation of ITGA2 expression to COL1A2, COL3A1, and COL5A1 involved in focal adhesion pathway." (PMID 33026975, 2020). "Overexpressed ITGA2 promoted the proliferation of ovarian cancer cells." (PMID 32202508, 2020). "As mentioned in the introduction, ITGA2 is overexpressed in several malignant tumors, but its expression level in ovarian cancer remains unclear." (PMID 32202508, 2020). "However, although previous investigations have provided a foundation for our research to a certain degree, the specific molecular mechanism of how ITGA2 promotes ovarian cancer proliferation and metastasis is still unclear." (PMID 32202508, 2020). "The results showed that the level of ITGA2 increased significantly in ovarian cancer." (PMID 32202508, 2020). "In summary, ITGA2 could be used as a new therapeutic target and prognostic indicator in ovarian cancer." (PMID 32202508, 2020). "Our findings suggest that knocking down ITGA2 could significantly reduce PTX resistance by ovarian cancer." (PMID 32202508, 2020). "Since FOXO1 is linked to cytotoxic stress induced by paclitaxel and contributes to drug-resistance in ovarian cancers, we supposed that ITGA2 might play an important biological role in drug-resistance in ovarian tumors." (PMID 32202508, 2020). "Furthermore, our results showed that the invasion ability of ovarian cancer cells correlated positively with the expression level of ITGA2." (PMID 32202508, 2020). "Furthermore, the invasion transwell assay showed that the invasion ability of ovarian cancer cells was enhanced with the overexpression of ITGA2." (PMID 32202508, 2020).
ovarian carcinoma (continued). "We also demonstrated the tumor-promoting effect of ITGA2 in ovarian cancer in vitro and in vivo." (PMID 32202508, 2020). "So, ITGA2 is potentially responsible for activating AKT signaling in ovarian cancer." (PMID 32202508, 2020). "Our ITGA2 site-specific determination of total glycosylation revealed also 7 N-glycosylation sites and 5 sialylation sites (N343, N460, N475, N699, and N1057) spanning the entire structural domains of ITGA2 with complex type sialylated glycans in human ovarian cancer cells." (PMID 34646995, 2021). "Thus, our data indicate that silencing ITGA2 could inhibit the aggressiveness of ovarian cancer in vitro." (PMID 32202508, 2020). "Therefore, we questioned whether ITGA2 might regulate the aggressive ability of ovarian cancer cells by activating the AKT pathway." (PMID 32202508, 2020). "Interestingly, our research suggests that ITGA2 could promote the phosphorylation of AKT in ovarian cancer, thereby enhancing the proliferation of ovarian cancer cells." (PMID 32202508, 2020). "Collectively, these results suggest that ITGA2 might be a prognostic biomarker of ovarian cancer." (PMID 32202508, 2020). "Inhibition of the JNK and Akt signaling pathways suppressed ITGA2 and VEGFC expression in M-Met5A cells as well as ovarian cancer-mesothelial cell adhesion." (PMID 36766725, 2023). "Here, we found that the mesothelial expression of ITGA2 and VEGFC was induced by macrophages and enhanced the adhesion of ovarian cancer cells to mesothelial cells." (PMID 36766725, 2023). "Knockdown of ITGA2 and VEGFC in M-Met5A cells significantly inhibited the adhesion of ovarian cancer cells." (PMID 36766725, 2023). "In this study, we demonstrated that CCL2 and CCL5 derived from macrophages induced mesothelial expression of the adhesion-related genes ITGA2 and VEGFC to increase the adhesion of ovarian cancer cells." (PMID 36766725, 2023). "Previous studies have shown that ITGA2 and VEGFC play important roles in the invasion and angiogenesis of various cancers, including gastric and ovarian cancer." (PMID 36766725, 2023). "Taken together, these data indicated that the JNK and Akt pathways regulate the mRNA expression of ITGA2 and VEGFC, thereby modulating the adhesiveness of M-Met5A cells toward ovarian cancer cells." (PMID 36766725, 2023). "ITGA2, VEGFC, and their regulatory pathways, JNK and Akt, play critical roles in increasing the adhesion of macrophage-stimulated mesothelial cells to ovarian cancer cells." (PMID 36766725, 2023). "Taken together, these data indicated that CCL2 and CCL5 secreted by macrophages can increase the expression of adhesion-related genes ITGA2 and VEGFC via the JNK and Akt pathways in Met5A cells, resulting in enhanced ovarian cancer-mesothelial cell adhesion." (PMID 36766725, 2023). "The results showed that there was a positive correlation between the protein levels of ITGA2 and the phosphorylation levels of AKT in ovarian cancer patients." (PMID 32202508, 2020). "Consequently, specific inhibition of ITGA2-mediated cancer cell-collagen interaction or targeting focal adhesion signaling may present an opportunity for therapeutic intervention of metastatic spread in ovarian cancer." (PMID 33026975, 2020). "To determine the clinical relationship between ITGA2 and p-AKT in human ovarian cancer specimens, we analyzed the protein expression level of ITGA2 and phosphorylation level of AKT in a cohort of ovarian cancer patients immunohistochemically (n = 65)." (PMID 32202508, 2020). "To explore the biological role of overexpressed ITGA2 in ovarian cancer progression even further, we established SKOV3, OVCAR3, and A2780 cell lines with stably overexpressed ITGA2." (PMID 32202508, 2020). "ITGA2 was significantly upregulated in high-grade serous ovarian cancers compared with normal counterparts, and overexpressed ITGA2 contributed to paclitaxel resistance via activation of the AKT pathway in ovarian cancer cells." (PMID 38702644, 2024).
ovarian carcinoma (continued). "To determine whether ITGA2 and VEGFC are involved in the enhanced adhesiveness of M-Met5A cells, we further investigated the effect of ITGA2 and VEGFC knockdown on ovarian cancer mesothelial cell adhesion." (PMID 36766725, 2023). "Combining ITGA2 knockdown with PTX treatment caused a more remarkable decrease in tumor volume and tumor mass, suggesting that knocking down ITGA2 could inhibit PTX resistance and also enhance the therapeutic ability of PTX in ovarian cancer in vivo." (PMID 32202508, 2020). "Blockade of either FAK or MAPK signaling axis showed no direct impact of cell-collagen adhesion but significantly reduced mesothelial clearance activity of EOC cells, supporting the functional involvement of ITGA2, and FAK/MAPK axis in ovarian cancer metastasis model." (PMID 33026975, 2020). "We also found that ITGA2 regulated the phosphorylation of forkhead box O1 (FoxO1) by mediating AKT phosphorylation, which provided a reasonable explanation for ITGA2’s role in ovarian cancer’s resistance to albumin paclitaxel." (PMID 32202508, 2020). "However, it remains uncertain how ITGA2 regulates AKT/Foxo1 axis and how ITGA2 is regulated in the ovarian cancer cells." (PMID 33026975, 2020). "Overexpression of ITGA2 promoted in vitro cancer cell aggressiveness and in vivo tumor growth through regulation of the phosphorylation of forkhead box O1 (FoxO1) and AKT phosphorylation, which provided the mechanism for ITGA2-mediated paclitaxel-resistance in ovarian cancer." (PMID 33026975, 2020). "Firstly, we did not investigate the reason for the increase in ITGA2 expression in ovarian cancer." (PMID 32202508, 2020). "In this study, we reveal that the ITGA2 protein increased in ovarian cancer tissues compared to normal ovarian tissues, and ITGA2 correlated significantly with the unfavorable prognosis of ovarian cancer, suggesting that ITGA2 could be regarded as a prognostic marker of ovarian cancer." (PMID 32202508, 2020).
prostate carcinoma (20 papers, 2009 to 2024). A carcinoma that arises from epithelial cells of the prostate gland. "Integrin ITGA2 (of α2β1) is initially a tumour suppressor gene in BC and prostate cancer (PC), its loss promoting metastasis, however metastatic cells increase ITGA2 expression to facilitate metastasis to bone." (PMID 36512308, 2023). "ITGA2 inhibition is associated with non-invasive prostatic cancer and reduced cell migration in colorectal cancer." (PMID 27359056, 2016). "As an example, ITGA2 (integrin alpha 2) was downregulated in parietal pleura, a membrane adhesion protein which polymorphisms are associated to breast and prostate cancer." (PMID 19662092, 2009). "The in vivo and in vitro findings were further correlated with analysis of microarray gene expression datasets of human breast and prostate cancers, which showed a correlation between decreased expression of ITGA2 and poor prognosis." (PMID 24985072, 2014). "By contrast, ITGA2 is expressed in both prostate cancer cell lines." (PMID 30542512, 2018). "However, some studies demonstrated that ITGA2 up-regulation mediated selective metastasis to different organs such as the liver in melanoma and bones in prostate cancer." (PMID 26258411, 2015). "We compared the expression levels of eight integrin subunits (ITGA2, ITGA5, ITGAV, ITGB1, ITGB3, ITGB4, ITGB5, and ITGB6), HOXB13, HOXA11-AS, CCL2, CXCL12, and IBSP in prostate cancer tissues that had metastasized to bone, lymph nodes, lungs, liver, and other organs." (PMID 33514011, 2021).
melanoma (19 papers, 2015 to 2026). A malignant, usually aggressive tumor composed of atypical, neoplastic melanocytes. "Our data show that high expression of OPNa, OPNb, and especially OPNc and low expression of OPN4 and ITGA2 are associated with an advanced stage of tumor progression and poor prognosis in melanoma." (PMID 36091936, 2022). "Our data show that high expression of OPNa, OPNb, and OPNc is associated with poor prognosis, and OPN4 and ITGA2 may have an opposite role in melanoma progression." (PMID 36091936, 2022). "ITGA2 plays a role in melanoma by regulating the expression GTSE1, thereby restoring the epithelial-to-mesenchymal transition in SKCM." (PMID 34660316, 2021). "In addition, we also took the GSE78220 cohort and the GSE91061 cohort to predict the prognosis of ITGA2 in melanoma." (PMID 34778054, 2021). "ZEB1 binding peaks were also found in other major markers of melanoma cell identity, namely BIRC3, ITGA2 and EGFR, which are up-regulated upon phenotype switching towards the ZEB1high state as confirmed by RT-qPCR." (PMID 38519642, 2024). "A significant difference in the gene expression level of ITGA2 was found in SSM tissue samples (median = −1.622) compared with NM (median = −3.630) and melanoma metastasis (median = −4.807) tissue samples." (PMID 36091936, 2022).
colon cancer (18 papers, 2013 to 2025). "Loss of ITGA2 expression was also found to be associated with metastasis of breast and colon cancer." (PMID 29912899, 2018). "Loss of ITGA2 expression was associated with enhanced tumor intravasation and metastasis of breast and colon cancer." (PMID 29121049, 2017). "Expression levels of Pcna, Ccnd1(CyclinD1), Bcl2, Itga2, Itgb1, Fak, Pik3r1, Akt1, Mtor and Myc were remarkably upregulated and Bax was downregulated in colonic tumors of mice treated with S. moorei." (PMID 39990665, 2025). "Pleckstrin homology like domain family A member 1 (PHLDA1) plays a crucial role in promoting the migration and proliferation of colon cancer cells by regulating the expression level of ITGA2 in colonic malignant tumors." (PMID 37881431, 2023). "ITGA2 gene was reported to play migrating roles in colon cancer cells, and it expressed in colorectal cancer with liver metastasis tissues but absent in normal tissue." (PMID 30428899, 2018). "ITGA2 is expressed in colon cancer cell lines and is involved in the proliferation and migration of these cells." (PMID 28947976, 2017). "Another study showed that ITGA2 was highly expressed and may have had an extensive impact on colon cancer through interacting with transcription factors." (PMID 34778054, 2021). "More and more evidence show that ITGA2 acts as a cancer-promoting protein to enhance tumor proliferation and metastasis, although there is still some evidence to the contrary in breast and colon cancers." (PMID 32202508, 2020). "LncRNA LINC00355 interacted with the ITGA2 promoter and recruited transcription factor GTF2B, upregulating ITGA2 to promote proliferation and metastasis of colon cancer." (PMID 36512308, 2023).